RAC1 (Rac family small GTPase 1)
Diseases named in the same sentence as RAC1 in open-access papers (continued):
Sharing a sentence is not in itself a finding about the gene and the disease.
tumor (continued). "Hyperactivation of KRAS in almost all tumours drives RAC1 activation, conferring enhanced migratory and proliferative capacity as well as macropinocytosis." (PMID 38712822, 2024). "Among these effects, we have already validated in the in vivo setting that constitutively active RAC1 is able to restore the lost tumor formation ability resulting from RAB4A knockdown." (PMID 39463384, 2024). "Further investigation into RAC1 in these cells showed that RAC1 drives the production of reactive oxygen species (ROS) and activating nuclear factor kappa B (NFκB) signaling to facilitate tumor progression." (PMID 39001533, 2024). "For instance, E3 ubiquitin ligase HACE1 downregulates Rac1 activity and functions as a suppressor in Rac1-mediated tumor progression." (PMID 38809020, 2024). "The HACE1 E3 ubiquitin ligase is a tumour suppressor that ubiquinates active RAC1 at the Lys147 residue, leading to its degradation." (PMID 40396280, 2024). "Our previous results demonstrate that mature IL-37b can bind directly to and inhibit RAC1, thereby inhibiting tumor metastasis." (PMID 38907105, 2024). "In tumors, the aberrant expression and activity of RAC1 have been extensively studied, particularly in the context of tumor invasion and metastasis processes." (PMID 38463514, 2024). "Administration of Rac1 inhibitors to mice bearing CRC tumors reduced tumor growth, sensitized resistant tumors to 5-FU monotherapy, and decreased metastasis development." (PMID 39513883, 2024). "Rac1 inhibition has an essential role to block cell migration, invasion and the rearrangement of the actinskeleton of different tumor cells." (PMID 38791951, 2024). "We conclude that quercetin exerts its anticancer effects via the modulation of Rac1-p66Shc signaling by specifically inhibiting Rac1 activation, thus restraining the production of ROS and tumor growth." (PMID 38362155, 2024). "In this study, we explored the effect of quercetin on Rac1/p66Shc-mediated tumor cell inflammation, which is the principal pathway for the generation of ROS in brain cells." (PMID 38362155, 2024). "Immunohistochemistry staining revealed that RAC1 was more localized in the cytoplasm of adjacent non-tumor tissues, while the staining was deeper in HCC tissues." (PMID 38378644, 2024). "Activated RAC1 mutations accelerate tumour growth, induces epithelial–mesenchymal transition (EMT), increases angiogenesis, and influences tumour microenvironment-mediated immune escape driving tumour metastasis and causing treatment failures." (PMID 40396280, 2024). "The E3 ubiquitin ligase HECT domain and ankyrin repeat containing E3 ubiquitin protein ligase 1 (HACE1) is a potent tumor suppressor that controls cellular proliferation and ubiquitylates the small GTPase RAC1 to target it for proteasomal degradation." (PMID 38169395, 2024). "Previous studies showed that the R‐enantiomer of ketorolac selectively inhibits Rac1 and Cdc42 and reduces tumour growth, invasion and metastasis." (PMID 38302863, 2024). "Activation of RAC1 is also reported to contribute to the evasion of cell death induced by chemotherapy or targeted therapies, leading to resistance and tumor recurrence." (PMID 39463384, 2024). "We previously reported that cytoplasmic IL-37 can localize on microtubes to inhibit Rac1 GTPase activity and, thus, tumor metastasis." (PMID 38907105, 2024). "RAC1 expression has been shown to be higher in liver metastases compared to primary CRC tumor cells, and inhibiting RAC1 decreases liver metastasis." (PMID 39001533, 2024). "Surprisingly, Rac1 inhibitor 1A-116 administration statistically affected the growth evolution of tumor cells." (PMID 39513883, 2024). "The expression of Rac1 is commonly observed in malignant tumor tissues, while the abnormal expression has been significantly associated with tumor growth, metastasis, and drug resistance." (PMID 38347626, 2024). "By employing inhibitors of Rho or Rac1, we demonstrated that neutrophil-mediated tumor killing is inhibited." (PMID 38806658, 2024).
tumor (continued). "Rac1 is highly expressed and overactivated in many tumor types, and it has lately been related to resistance to therapy in several reports." (PMID 39513883, 2024). "Recently, attention has shifted to Rac1 and its inhibition as a strategy to impede tumor cell movement." (PMID 38791951, 2024). "Due to its crucial role in tumor development, Rac1 has become a standard for tumor stratification and a promising therapeutic target." (PMID 38344200, 2024). "The presence or absence of the EPS8/SOS1/ABI1 complex acts as a molecular switch in PDAC cells to balance RAC1 and RhoA activation to promote tumor migration or TGFβ activation, respectively." (PMID 39354505, 2024). "To ascertain the in vivo implications of HACE1 inhibition of ESCA and the potential involvement of RAC1, we conducted tumor-bearing nude mouse experiments, employing a RAC1 inhibitor to block the RAC1 pathway." (PMID 38706891, 2024). "Animal experiments concurred, displaying that TRIP12 silencing mitigated HACE1's inhibitory impact on tumor growth and RAC1 protein levels in tumor tissue." (PMID 38706891, 2024). "RAS-related C3 botulinum toxin substrate 1 (Rac1) is involved in regulating various aspects of the tumor cell cycle, apoptosis, proliferation, invasion, migration, and angiogenesis." (PMID 39118792, 2024). "Cdc42 and Rac1 are important therapeutic targets in ovarian cancer since these two proteins play a critical role in tumor cell migration, adhesion, and invasion." (PMID 39769207, 2024). "Deletion of RAC1 in a KRAS-driven mouse model of PDAC delayed tumour onset, reduced PanIN lesions, and improved survival." (PMID 38712822, 2024). "Studies have reported that RAC1 can promote tumor progression through the P38/MAPK, WNT, ERK, and other pathways." (PMID 39224538, 2024). "Through cell function tests and in vivo tumor formation tests, we found that RAC1 can promote tumor growth by mediating paclitaxel (PTX) resistance." (PMID 39224538, 2024). "Given the important roles of RAC1 and RAC1B in CRC tumor biology and progression described in this review, inhibiting RAC1 and RAC1B is a potential therapeutic option." (PMID 39001533, 2024). "RhoGDI2 has also been shown to act as a tumour and metastasis suppressor in OV cancer by enhancing Rac1 activity to activate p38 and JNK/MAPK cascades." (PMID 36835422, 2023). "Mechanistically, ARHGAP15 inactivated RAC1 and then decreased intracellular accumulation of reactive oxygen species (ROS), thus enhancing the antioxidant capacity of colonizing tumor cells under oxidative stress." (PMID 36802400, 2023). "Rac1 is the node at which multiple signaling pathways such as tumor proliferation, invasion, and movement converge." (PMID 37970440, 2023). "Because of its crucial role in tumor metastasis, Rac1/PAK1 is widely used as a target for antitumor treatment." (PMID 37049739, 2023). "Rac1-induced ROS generation affects actin cytoskeleton reorganization, leading to cell migration and invasion of various tumor cells." (PMID 37202394, 2023). "RAC1 was expressed in every cell type, however its expression was significantly higher in three tumor populations." (PMID 37007745, 2023). "RAC1 signaling is upregulated in various cancers, including breast cancer, and regulates cellular processes such as tumor cell survival, proliferation and invasion." (PMID 36599922, 2023). "We next analyzed the RAC1 CN status in the tumor samples, displaying either diploid or amplified CBX3 gene." (PMID 37633946, 2023). "T lymphoma invasion and metastasis 1 (Tiam1) is a tumor related gene that specifically activates Rho-like GTPases Rac1 and plays a critical role in the progression of various malignancies." (PMID 38017477, 2023).
tumor (continued). "Our results indicated that targeting inhibition or down-regulation of CD36 in LUAD cells significantly reduced tumor cell proliferation and metastasis, in which Src-Akt/Erk signaling and Rac1 activation-induced actin remodeling were involved." (PMID 37612265, 2023). "Increasingly, studies are reporting the role of Rac1 in tumor invasion or metastasis and are, therefore, suggesting that Rac1 is a potential target for tumor therapy." (PMID 37049739, 2023). "One study shows that the targeting of NCKAP1 to block Rac1-Scar/Wave signaling can slow tumor progression and possibly enhance immune infiltration." (PMID 37049739, 2023). "Further studies revealed that mitochondrial fission promoted the mobility, migration, and invasion of the tumor by regulation of metabolic reprogramming, Ca2 + -driven motility, lamellipodia formation, and ROS-mediated Rac1 activation and F-actin assembly." (PMID 36922509, 2023). "One study has demonstrated that DEPDC1B can promote tumor cell invasion and migration by activating the Rac1/PAK1/LIMK1/cofilin pathway." (PMID 37049739, 2023). "The level of Rac1 activity is important for its function in tumor cell migration, invasion and metastasis." (PMID 37049739, 2023). "This anti-tumor activity was further corroborated by down regulation of Rac-1/Cdc42/HIF-1α/DDX3/β-catenin signalling." (PMID 37024613, 2023). "miR-124 regulates the expression of the RAC1 (Rac family small GTPase 1) oncogene and inhibits tumor cell proliferation." (PMID 37373398, 2023). "Like SDC4, the CD44 cytoplasmic domain is reported to mediate cell migration through Rac1 and RhoA in human tumor cell lines." (PMID 36735684, 2023). "After the knockdown of CTTN by CTTN RNA interference (RNAi), changes in tumor cell invasive and migratory abilities, pseudopodia, and Rac1 protein expression were observed, and the invasion and migration mechanisms of EC cells were studied." (PMID 37970440, 2023). "Clarifying the complex regulatory network and the role of Rac1 in tumor tolerance and immunotherapy will contribute to developing more effective inhibitors and/or drugs targeting Rac1." (PMID 37049739, 2023). "In this review, we summarize the role of Rac1 in cell migration, tumor invasion and metastasis, and the regulatory mechanisms involved." (PMID 37049739, 2023). "It has been shown that Rac1 is involved in an array of biological functions, including cell motility and tumor metastasis, as well as endocytic and exocytic transport." (PMID 38203692, 2023). "Transitional phase related gene analysis identified RAC1 was enriched in metastatic tumor tissue (MTT) preferred gene set functioning as regulated cell death and apoptosis as well as promoted macromolecule organization." (PMID 37202394, 2023). "Further studies indicated that ARHGAP15 suppressed RAC1 and then decreased intracellular reactive oxygen species produced by NOX2, a downstream gene of RAC1, thus protecting colonizing tumor cells from oxidative stress." (PMID 36802400, 2023). "Rac1 receives upstream signals and transfers them to the cytoskeleton, thus regulating tumor cell migration." (PMID 37049739, 2023). "GLS2 exhibits a tumor-suppressive function by inhibiting Rac1 activity, which in turn inhibits the migration, invasion and metastasis of malignancy cells." (PMID 37754250, 2023). "The inhibition of Rho GDP differentiation inhibitor 2 (RhoGDI2) can also reduce tumor cell migration by downregulating Rac1/PAK1/LIMK1." (PMID 37049739, 2023). "Here we have identified FilGAP, a GTPase-activating protein (GAP) for Rac1, as a negative regulator of invadopodia formation in tumor cells." (PMID 37482421, 2023). "Dual loss-of Rac1 and Rac1b functions in MMTV-NIC mouse model delays tumor latency in a dose-dependent manner." (PMID 36599922, 2023). "Some natural products with antitumor activities, such as zerumbone and genistein, inhibit tumor cell migration and invasion by suppressing Rac1 expression or the Rac1-related signaling pathway." (PMID 37049739, 2023).
tumor (continued). "These functions of Rac1 become crucial for angiogenesis and tumor promotion, invasion, and metastasis." (PMID 36672323, 2023). "Conversely, whereas up to 95% of NSCLC samples, which are diploid for CBX3 are also normoploid for RAC1 gene, 95% of tumor samples harboring multiple copies in CBX3 gene display low gain increase in RAC1 CN." (PMID 37633946, 2023). "We also unveiled that in addition to co-occurrence of gene amplification among CBX3, EGFR and RAC1, also low-grade CNVs of these genes strongly co-occur in several human tumor types and are much more recurrent than high-grade CNVs." (PMID 37633946, 2023). "Targeting negative regulatory factors can indirectly regulate Rac1-Scar/Wave-Arp2/3 to suppress tumor metastasis." (PMID 37049739, 2023). "Rho GTPases, a kind of regulator for intracellular actin dynamics, mainly consisting of RhoA, Rock1/2, Cdc42, and Rac1, can dramatically interfere with the motility of tumor cells." (PMID 36969843, 2023). "In this study, we found ARHGAP15 inhibited the activity of RAC1 to alleviate intracellular ROS accumulation, thus protecting tumor cells from oxidative stress induced cell death." (PMID 36802400, 2023). "One study has shown that abnormal nuclear accumulation of Rac1 leads to nuclear deformation and high RhoA activity in cytoplasm, which favors matrix degradation and the invasion of tumor cells." (PMID 37049739, 2023). "For example, in adult T cell leukemia/lymphoma (ATL), the activity of RAC1 is observed to be related to the formation of lamellipodia for the enhancement of tumor cell infiltration." (PMID 36552804, 2022). "In the case where Rac1 activity is beyond the lowest threshold, development is perturbed instead of tumoregenesis, whereas when Rac1 activity exceeds its highest threshold, cells are hyper-proliferated and thereby forming the tumor." (PMID 35154488, 2022). "Beyond its pro‐migratory potential, Rac1 is a critical modulator of several other hallmarks of cancerogenesis such as tumour cell proliferation, anti‐apoptotic mechanisms, drug resistance and angiogenesis." (PMID 36377725, 2022). "Xenograft-bearing mice were treated with 8 mg/kg or 16 mg/kg TBOPP by intravenous injection twice a week, and the results showed that 8 mg/kg of TBOPP inhibited the activation of RAC1 but exhibited only modest suppression of tumor growth and mouse body weight." (PMID 35217990, 2022). "Like other GTPases, RAC1 switches between an active, GTP-bound state and an inactive, GDP-bound state, and the active form GTP-RAC1 is involved in the regulation of malignant behaviors of tumor cells." (PMID 35858925, 2022). "Tumor cell migration is a complex biological process in which Rac1, cofilin and Arp2/3 play key roles, form lamellipodia, and determine the direction of cell movement." (PMID 35593474, 2022). "Tumour sphere assay indicated that the self‐renewal ability of cells with DAB2IP‐inhibition was weakened by RAC1‐inhibition." (PMID 36536485, 2022). "The model showed that patients with lower tumor stage, higher RAC1 methylation levels, WT NTRK3, higher Tr cell infiltration in the TME, and RASA1 CNV survived better than other patients with opposite status." (PMID 35936718, 2022). "Tumor stage and RAC1 methylation contributed the most to DSS prediction, with a wide range of points." (PMID 35936718, 2022). "To explore the mechanism underlying CSDE1-related tumor progression in TNBC, we verified that Rac1 expression was regulated by CSDE1 in TNBC." (PMID 35490208, 2022). "In contrast, circ_0004458 silenced suppressed cell growth and enhanced apoptosis and cell cycle arrest in PTC cell lines in vitro, and hampered tumor growth in nude mice by inhibiting miR-885-5p and activating “Rac family small GTPase 1 (RAC1)”." (PMID 36230649, 2022).
tumor (continued). "In normal brain specimens, Rac1 mRNA expression is lower but is increased with increasing tumor grade and is significantly higher in GBM samples." (PMID 36230732, 2022). "In this study, we identified MG53 as a novel regulator of RAC1 and verified that MG53 exerted its anti-tumor effect by directly interacting with RAC1 and inducing the ubiquitination-mediated degradation of RAC1 in HCC." (PMID 35858925, 2022). "The increase in RAC1 expression indicates the diverse interactions between different cells, which exacerbate the degree of tumor malignancy." (PMID 36354566, 2022). "Our research revealed that RAC1 was upregulated in a variety of tumors and was related to tumor prognosis." (PMID 35534866, 2022). "Altogether, these data collectively demonstrated that MG53 exerted its anti-tumor effect on HCC cells through its effective inhibition of RAC1-MAPK signaling axis." (PMID 35858925, 2022). "Of note, the p.Q61L variant is best characterized as a GTPase-defective constitutively active version of RAC1 involved in tumour cell metastasis and invasion." (PMID 35851598, 2022). "Previous studies have demonstrated that RAC1 plays an important role in the regulation of tumor progression." (PMID 35858925, 2022). "Previous studies reported that ARHGAP24 was a Rac-specific RhoGAP, inactivating Rac1 and thereby inhibiting tumor progression." (PMID 36168627, 2022). "In the xenograft tumor tissue overexpressing circBRWD3, RAC1, PAK1, and p- PAK1 were dramatically upregulated, while in the tissue with circBRWD3 knockdown, they were significantly downregulated." (PMID 36443711, 2022). "The most plausible mechanism for RAC1/P29S in tumor progression is through activation of the serum response factor/myocardin-related transcription factor (SRF/MTRF) transcriptional programs, which lead to mesenchymal transition of melanocytes." (PMID 35454871, 2022). "In particular, in ALL patients they observe a CD9-mediated overexpression of the RAC1 protein, an important mediator of cell migration and tumor progression." (PMID 35955786, 2022). "The OS nomogram model shared the predictors of tumor stage, RAC1 methylation, and Tr cell infiltration of DSS." (PMID 35936718, 2022). "Under the action of PI3K (phosphatidylinositol 3 phosphate), Rac1-GDP can be converted into Rac1-GTPase, thereby activating tumor metastasis-related transduction pathways in which Rac1 is involved." (PMID 35682879, 2022). "Rac1-Pak1 signaling affects tumor cell proliferation, migration, metastasis, angiogenesis, and drug- and radio-resistance." (PMID 35327364, 2022). "We found that tumor stage, Tr1 infiltration, and RAC1 methylation were important for DSS and OS nomograms." (PMID 35936718, 2022). "Our research performed that the upregulation of Rac1 in tumor was related to poor prognosis in HCC patients." (PMID 35847360, 2022). "The wound healing and EdU assays demonstrate that the promoting effects of LAPTM5 on tumor proliferation were significantly weakened following RAC1 inhibitor treatment." (PMID 36385959, 2022). "Specific inhibitors or gene knockout to inhibit the activity or expression of Rac1 can inhibit tumor invasion, metastasis, and other malignant behavior." (PMID 35847360, 2022). "EGFR signaling generally follows the PAK1/Rac1 route to convey the signal and to regulate tumor progression." (PMID 35740379, 2022). "Tumor stage, RAC1 methylation, and type 1 regulatory T cells greatly contributed to DSS and OS nomograms." (PMID 35936718, 2022). "At present, more and more evidences show that the abnormal activity and expression of Rac1 are closely related to tumorigenesis, survival, metastasis, antiapoptosis, drug resistance, and other tumor characteristics." (PMID 35847360, 2022). "Rac1, as one of a member of the Rho family GTPases, exerted great influence on tumor occurrence and development." (PMID 35953862, 2022).